CDPF1 (cysteine rich DPF motif domain containing 1)
Synonyms: C22orf40; CDKN1A
Tractability: No criterion of Open Targets' tractability assessment is met for any kind of drug.
Gene: Protein-coding gene on chromosome 22 (46,244,011 to 46,250,311, reverse strand). Ensembl gene ENSG00000205643.
Subcellular location (Human Protein Atlas): Cytosol; Nucleoplasm
Gene Ontology:
Molecular function: protein binding
Genetic constraint (gnomAD): Loss-of-function variants: 6 observed, 7.38 expected, observed/expected ratio (o/e) 0.81, 90% interval 0.44 to 1.57. That is too few expected variants to judge how well the gene tolerates losing a copy. Missense variants: 145 observed, 155.62 expected, observed/expected ratio (o/e) 0.93, 90% interval 0.81 to 1.07. Synonymous variants: 58 observed, 62.55 expected, observed/expected ratio (o/e) 0.93, 90% interval 0.75 to 1.15.
Homologues: Orthologues: chimpanzee CDPF1 (94% identical), macaque CDPF1 (93% identical), dog CDPF1 (84% identical), rabbit CDPF1 (79% identical), pig CDPF1 (76% identical), guinea pig CDPF1 (76% identical), mouse Cdpf1 (73% identical), rat Cdpf1 (72% identical), tropical clawed frog cdpf1 (59% identical), zebrafish cdpf1 (52% identical), Drosophila melanogaster CG11755 (30% identical), Caenorhabditis elegans D2089.8 (28% identical), and 1 more.